BRCA2 (BRCA2 DNA repair associated)
Diseases named in the same sentence as BRCA2 in open-access papers (continued):
Sharing a sentence is not in itself a finding about the gene and the disease.
breast cancer (continued). "As deleterious germline mutations in BRCA1 and BRCA2 confer a greatly increased risk of breast cancer, some sequence variants in both genes might be candidates for moderate or low penetrance alleles." (PMID 18489799, 2008). "Finding new immunohistochemical markers that are specific to hereditary breast cancer could help us to select candidates for BRCA1/BRCA2 mutation testing and to understand the biological pathways of tumour development." (PMID 18275599, 2008). "In a study of 173 families with BRCA2 mutations, the Breast Cancer Linkage Consortium reported in 1999 that there was a significantly increased risk of prostate cancer among male first-degree relatives of female carriers." (PMID 18577985, 2008). "However, we observed that among the BRCA2 mutation-positive cases, carriers of the Ins16minus-72Arg haplotype had a significantly younger mean age of diagnosis of breast cancer compared to the other individuals within this group." (PMID 18402691, 2008). "Since the discovery of BRCA1 and BRCA2, numerous genes have been associated with a moderate increase in risk and are thought to interact in a polygenic inheritance mode to increase the susceptibility for breast cancer." (PMID 19077293, 2008). "In addition, male BRCA1 and (to a greater extent) BRCA2 carriers are at an increased risk of developing breast cancer, (DF Easton, unpublished data)." (PMID 18349832, 2008). "Thus, breast cancer risks in large familial breast cancer kindreds with BRCA1/BRCA2 mutations are substantially higher than risks derived from population based studies." (PMID 18513387, 2008). "Patients with either BRCA1 or BRCA2 germ-line mutations have an average risk of 39% and 11% respectively of developing ovarian cancer by the age of 70; they have a risk of 35-85% of developing breast cancer in their lifetime." (PMID 22275985, 2008). "We found that the best predictive factors for the presence of a BRCA1 or BRCA2 mutation are families with at least two cases of breast cancer, at least one of which occuring before the age of 50 (p = 0.0335), and families with a history of both breast and ovarian cancer (p < 0.0001)." (PMID 18627636, 2008). "As deleterious germline mutations in BRCA1 and BRCA2 confer a greatly increased risk of breast cancer, some sequence variants may be only moderate or low penetrant alleles." (PMID 18489799, 2008). "Moreover, the BRCA2-8765delAG mutation has been demonstrated to be present in all affected individuals from the four (57%) out of seven breast cancer families who shared an identical-by-descent haplotype within North Sardinia." (PMID 17640379, 2007). "Recently we showed that diagnostic ionising radiation exposure from chest X-rays may be associated with a significantly increased breast cancer risk among women who carry BRCA1 or BRCA2 pathogenic germline mutations." (PMID 17428320, 2007). "In a meta-analysis of such case-based studies, by age 70 years, in BRCA1 carriers breast cancer risk was 65% (95% CI 51–75%) and ovarian cancer risk was 39% (95% CI 22–51%), and in BRCA2 carriers breast cancer risk was 45% (95% CI 33–54%) and ovarian cancer risk was 11% (95% CI 4.1–18%)." (PMID 17213823, 2007).
breast cancer (continued). "Breast cancer arising due to a high penetrance genetic predisposition gene such as BRCA1 or BRCA2 occurs at younger average age than breast cancer in the general population and a higher proportion of young onset cases will have a genetic predisposition than breast cancer cases in general." (PMID 17697367, 2007). "However, in some studies, OC use has been found to increase breast cancer risk among women with known BRCA1 or BRCA2 germline variants." (PMID 17553133, 2007). "Thus, polymorphisms in the regulatory region of the BRCA2 gene, which can modulate the fine-tuned regulation of its expression, are logical candidates to provide risk for breast cancer." (PMID 17945002, 2007). "Common polymorphic variants in BRCA1 and BRCA2 genes may represent breast cancer (BC) susceptibility alleles and could be associated with a modestly increased risk of MBC at population level." (PMID 17767707, 2007). "Although earlier estimates suggested that BRCA1 and BRCA2 mutations were responsible for 75% of breast cancer families recent population-based studies indicate that these rates may have been overestimated." (PMID 16764716, 2006). "Using rigorously controlled semiquantitative RT–PCR and densitometry analysis, we found that a dose of I3C (60 μM) that causes little or no cytotoxicity caused a time-dependent increase in BRCA1 and BRCA2 mRNA levels in two breast cancer cell lines, MCF-7 and T47D." (PMID 16434996, 2006). "These therapeutic agents could also be effective for sporadic breast cancers with abnormalities in the BRCA genes, which is, as shown here, a considerably larger proportion of all breast cancer patients than germline BRCA1 or BRCA2 mutation carriers." (PMID 16846527, 2006). "However, this combination missed the same BRCA2 mutation-positive family (the two sisters with breast cancer at the ages 47 and 52 and one brother with pancreatic cancer) as none of the ‘additional criteria’ were fulfilled." (PMID 16909138, 2006). "The effects of heterozygous mutations in the BRCA1 or BRCA2 breast cancer-predisposing genes on the endocrine sensitivity of human breast epithelial cells are unknown." (PMID 16538216, 2006). "Since the IVS16-2A>G mutation can result in either a partial or total skipping of exon 17, the increased risk for breast cancer in males due to this mutation may be related to these effects on BRCA2 gene transcription." (PMID 16764716, 2006). "However, BRCA2 carriers who had two or more therapeutic abortions faced a 64% decrease in the risk of breast cancer (odds ratio = 0.36; 95% confidence interval 0.16–0.83; p = 0.02)." (PMID 16563180, 2006). "Previous analyses of French Canadian population have also shown that these recurrent BRCA1 and BRCA2 mutations accounted for about 13% (diagnosis before age 41 years) and 3% (diagnosis before 80 years of age) of breast cancer cases and 8% of ovarian cancer cases." (PMID 16539696, 2006). "BRCA1 and BRCA2 are the most important breast cancer susceptibility genes identified to date." (PMID 16417652, 2006). "Carriers of BRCA1 and BRCA2 mutation(s) are also at increased risk for other cancers – in particular, both genes increase the risk of ovarian cancer, while BRCA2 confers greatly increased risks of male breast cancer." (PMID 17018160, 2006). "A significant proportion of breast and/or ovarian cancer families of French Canadian descent harbour specific recurrent mutations in BRCA1 and BRCA2 which confer a significantly increased lifetime risk of developing young age of onset breast cancer and ovarian cancer." (PMID 16539696, 2006). "BRCA1 or BRCA2 germline mutations increase the risk of developing breast cancer." (PMID 16846527, 2006). "However, induction of progesterone receptor expression by E2 was impaired in the tissue taken from BRCA1 and BRCA2 carriers compared to that taken from women at population risk of breast cancer." (PMID 16538216, 2006).
breast cancer (continued). "Mutations in the BRCA2 gene are one of the two major causes of hereditary breast cancer." (PMID 16280055, 2005). "We performed a matched case–control study to investigate whether or not there is an association between changes in body weight and the risk of breast cancer in women with a deleterious BRCA1 or BRCA2 mutation." (PMID 16168130, 2005). "Retrospective cohort studies considering breast cancer survival in BRCA1 or BRCA2 mutation carriers may suffer from ascertainment and testing bias." (PMID 16052221, 2005). "We genotyped 3,241 cases of breast cancer diagnosed at under 51 years of age, unselected for family history, from 18 hospitals throughout Poland and 2,791 ethnic-matched controls for a single BRCA2 C5972T variant." (PMID 16280055, 2005). "We sought to determine whether this common missense BRCA2 variant plays a role in breast cancer susceptibility." (PMID 16280055, 2005). "Interestingly, prophylactic oophorectomy in BRCA1 and BRCA2 mutation carriers under the age of 40 years causes a 60% reduction in the risk of developing breast cancer." (PMID 16457695, 2005). "We conducted our study to examine whether change in body weight modifies the risk of breast cancer among women who carry a deleterious BRCA1 or BRCA2 mutation." (PMID 16168130, 2005). "BRCA1 and BRCA2 mutations have been detected in quite a low proportion of breast cancer families." (PMID 15642173, 2005). "Later studies estimated even higher incidences of contralateral breast cancer within the first 5 years of follow-up after the primary breast cancer: 12–33% among BRCA1 or BRCA2 mutation carriers (2.4–6.5% per year) as compared to a 0.4–1% per year for breast cancer patients in general." (PMID 16052221, 2005). "However, Weber and coworkers recently described EGFR missense mutations in sporadic and familial (BRCA1/BRCA2 related) breast cancer and demonstrated that these mutations are significantly more frequent in the latter." (PMID 16280056, 2005). "BRCA1 and BRCA2 are the two principal hereditary breast cancer susceptibility genes, and the prevalence of their mutations among Brazilian women is unknown." (PMID 16389418, 2005). "Seven tumors were sporadic with unknown mutations, whereas the remainder were familial cancers, in which one of the known genes associated with breast cancer was mutated: BRCA1 (7 patients) or BRCA2 (8 patients)." (PMID 16018805, 2005). "However, BRCA2 mutation prevalence in sporadic male breast cancer has been found to be as high as 33 and 21% in the Hungarian and Swedish population." (PMID 15026808, 2004). "BRCA1 and BRCA2 are the most important susceptibility genes for breast and ovarian cancer, and mutations in these two genes account for >80% of all kindreds with hereditary breast/ovarian cancer and for about 2–3% of breast cancer (BC) cases overall." (PMID 14735197, 2004). "A male breast cancer case was indicative of a BRCA2 mutation segregating in the family (P=0.002)." (PMID 15026808, 2004). "Male breast cancer was indicative of a BRCA2 mutation segregating in the family (P=0.002)." (PMID 15026808, 2004). "Our finding of four cases of lobular breast cancer in this family is consistent with results from our previous hospital-based series of breast cancers from Montreal, where we identified four BRCA2 mutation carriers among 127 women with first primary invasive BCs." (PMID 14735197, 2004). "In addition to the breast and ovarian cancer risks, there is evidence that BRCA1 and BRCA2 mutations confer increased risks of other cancers such as prostate cancer and pancreatic cancer." (PMID 15381934, 2004). "It would be interesting to investigate whether polymorphisms in other oestrogen metabolism genes would influence breast cancer risk in BRCA2 carriers." (PMID 12644832, 2003).
breast cancer (continued). "We were also interested to see whether the CYP17 polymorphism could act as a modifier of breast cancer risk in female BRCA2 mutation carriers." (PMID 12644832, 2003). "However, it is consistent with the prediction of roughly equal prevalence of BRCA1 and BRCA2 mutations, based on a survey of very early onset breast cancers." (PMID 12698193, 2003). "To estimate more precisely the shape of the incidence curves for BRCA1 and BRCA2 mutation carriers, we fitted a model where separate breast cancer relative risks were assumed for ages 20–39, 40–49, 50–59 and 60–79 years, for both BRCA1 and BRCA2 mutation carriers." (PMID 11857015, 2002). "Thus, BRCA2 mutations are estimated to confer a breast cancer risk which is similar to the population risk but 10–12 times greater." (PMID 11857015, 2002). "In computing the probability that a woman is a BRCA1 or BRCA2 carrier for genetic counselling purposes, it is important to allow for the fact that other breast cancer susceptibility genes may exist." (PMID 11857015, 2002). "In conclusion, the high prevalence of AI at BRCA1 in BRCA2 mutation tumours and vice versa suggests that somatic events occurring at the other breast cancer susceptibility gene locus may be selected in the cancer development." (PMID 11710835, 2001). "To confirm several recent studies pointing to loss of heterozygosity (LOH) at BRCA2 as a prognostic factor in sporadic breast cancer, we examined this genetic alteration in a large series of human primary breast tumours for which long-term patient outcomes were known." (PMID 9400936, 1997). "We have examined the hypothesis that expression of the BRCA2 gene may be suppressed in sporadic breast cancers by a mechanism that is associated with increased methylation of cytosine residues in the promoter region." (PMID 9365162, 1997). "In the context of high-risk families the most important genes are BRCA1 on chromosome 17q, which is associated with a high penetrance of both breast and ovarian cancer, and BRCA2 on chromosome 13q, which causes a high risk of breast cancer but a lower risk of ovarian cancer." (PMID 7547224, 1995). "However, recently another candidate tumour-suppressor gene has been identified on chromosome 13 by linkage analysis, the breast cancer susceptibility gene BRCA2." (PMID 7577475, 1995). "Studies have shown that tumors with BRCA2 mutations demonstrate enhanced sensitivity to DNA-damaging chemotherapy through failure to repair double-strand breaks, with overall response rates exceeding those of sporadic breast cancers treated with anthracycline-based regimens." (PMID 41614924, 2026). "Furthermore, hereditary mutations in breast cancer gene 1 and breast cancer gene 2 (BRCA1 and BRCA2) may even increase the risk of breast cancer." (PMID 40507272, 2025). "In addition to the uncertainty about the spectrum of cancers associated with BRCA2, the reported penetrance for each cancer type in carriers varies considerably, ranging from 30% to 80% for breast cancer, 13%–29% for ovarian cancer, 5%–10% for pancreatic cancer, and 19%–61% for prostate cancer." (PMID 40462315, 2025). "Interestingly, in the South-East Asia (SEA) population, the BRCA2 mutation c.1763_1766delATAA (N588Sfs*612) was only ever reported in a breast cancer patient in Sarawak, Malaysia who was diagnosed at <40 years old with triple negative breast cancer and family history of breast cancer." (PMID 40531958, 2025). "However, the recent BRIDGES study has reported the presence of a few undisclosed BRCA2-PBD variants among patients with breast cancer, which could subsequently be explored to identify the PS4 strength of these variants." (PMID 40232841, 2025).
breast cancer (continued). "Women with germline pathogenic variants (PVs) in BRCA1 or BRCA2 genes have a significantly increased lifetime risk for breast cancer (BC) compared with the general population." (PMID 40042736, 2025). "In our study, we examined the breast cancer susceptibility associated with two SNPs in BRCA1 (rs386833395) and BRCA2 (rs80359550) through a case-control study involving 335 BC patients and 354 healthy controls." (PMID 40158114, 2025). "For example, the inclusion of genetic markers, such as BRCA1 and BRCA2, may improve breast cancer risk prediction but may be unfeasible to deploy in population-wide screening programs due to costs, lab-related analysis burden, ethical concerns, and time delays." (PMID 41146041, 2025). "In this analysis of women with a BRCA1 or BRCA2 mutation, we explored whether there was an association between infertility per se, as well as the treatment of infertility, and the risk of developing breast cancer." (PMID 41214587, 2025). "Moreover, new primary breast cancers may arise in BRCA1 or BRCA2 variant carriers due to inherent genetic susceptibility." (PMID 40366658, 2025). "PARP inhibitors (PARPis) induce synthetic lethality in BC patients carrying loss-of-function mutations in breast cancer susceptibility gene 1 (BRCA1) and BRCA2 and are routinely used in the clinical treatment of metastatic BC." (PMID 40649751, 2025). "In addition, the AFR population also exhibited a higher frequency of additional variants associated with breast cancer predisposition: BRCA2 (OR 2.24 [95% CI (1.31, 3.84), logistic regression p = 0.0031]) and PALB2 (OR 2.92 [95% CI (2.04, 4.19), logistic regression p = 5.8 × 10−9])." (PMID 40394000, 2025). "Hereditary BC is most often caused by mutations in the breast cancer 1 (BRCA1) or breast cancer 2 (BRCA2) genes." (PMID 40647408, 2025). "Besides that, BRCA2 mutations increase the risk of developing breast cancer in males." (PMID 41541272, 2025). "BRCA2 mutation may negatively affect disease-free survival in pregnant patients with breast cancer." (PMID 41164137, 2025). "Moreover, the literature implies that women with BRCA1 mutations have an average cumulative breast cancer risk of 65% by age 70, while those with BRCA2 mutations have a corresponding risk of 45%, based on pooled data from 22 studies of individuals unselected for family history." (PMID 40904409, 2025). "Similarly, the presence of BRCA1/BRCA2 mutations in breast cancer patients may influence the risk of complications after radiation, like brachial plexopathy, though the data is conflicting." (PMID 40191738, 2024). "Additionally, oncologists may even consider bilateral mastectomy as a primary surgical treatment for breast cancer due to the elevated rate of ipsilateral and contralateral breast cancer in patients with BRCA2 mutations." (PMID 39126233, 2024). "Furthermore, mutations in BRCA1 and BRCA2 genes are responsible for 5–10% of breast cancer cases." (PMID 39125744, 2024). "Additionally, mutations in certain genes, whether inherited or acquired, such as BRCA1 and BRCA2 (breast cancer susceptibility genes 1 and 2), can lead to the development of BC." (PMID 39598531, 2024). "In addition, mutation cluster regions are different between breast and ovarian cancers: mutations in the N-terminus and the C-terminus regions of BRCA2 increase the risk of developing breast cancers, whereas mutations in the central region have been linked with ovarian cancers." (PMID 37956396, 2024). "Women with germline BRCA1 or BRCA2 pathogenic variants (PV) account for 5% of all breast cancer (BC) and 15% of all OC." (PMID 39624976, 2024).